OR2C3 (olfactory receptor family 2 subfamily C member 3)
Description:
Odorant receptor.
Synonyms: OR2C4; OR2C5P; OST742; GCSAML-AS1
Tractability: Antibody: its Gene Ontology location is reachable by antibodies, with high confidence; UniProt places it where antibodies can reach, with medium confidence; UniProt predicts a signal peptide or a membrane-spanning region; the Human Protein Atlas places it where antibodies can reach.
Gene: Protein-coding gene on chromosome 1 (247,524,677 to 247,536,440, reverse strand). Ensembl gene ENSG00000196242.
Subcellular location: Cell membrane
Subcellular location (Human Protein Atlas): Plasma membrane
Pathways (Reactome):
Sensory Perception: Expression and translocation of olfactory receptors
Gene Ontology:
Molecular function: olfactory receptor activity; G protein-coupled receptor activity
Biological process: detection of chemical stimulus involved in sensory perception of smell; G protein-coupled receptor signaling pathway
Cellular component: plasma membrane; membrane
Genetic constraint (gnomAD): Loss-of-function variants: 0 observed, 0.36 expected, observed/expected ratio (o/e) 0, 90% interval 0 to 1.86. That is too few expected variants to judge how well the gene tolerates losing a copy. Missense variants: 425 observed, 423.53 expected, observed/expected ratio (o/e) 1, 90% interval 0.93 to 1.09. Synonymous variants: 178 observed, 173.93 expected, observed/expected ratio (o/e) 1.02, 90% interval 0.9 to 1.16.
Homologues: Orthologues: chimpanzee OR2C3 (98% identical), macaque OR2C3 (95% identical), rabbit OR2C3 (84% identical), pig OR2C3 (83% identical). Paralogues in human: OR2G2 (57% identical), OR2G3 (57% identical), OR2G6 (57% identical), OR2C1 (56% identical), OR2J2 (56% identical), OR2J1 (55% identical), OR2J3 (55% identical), OR2W1 (54% identical), OR2B6 (54% identical), OR2H2 (54% identical), OR2W3 (54% identical), OR2Y1 (53% identical), and 80 more.
Diseases named in the same sentence as OR2C3 in open-access papers:
OR2C3 is named in the same sentence as 3 diseases in open-access papers, as found by Europe PMC text mining. Sharing a sentence is not in itself a finding about the gene and the disease. The quoted sentences say what the papers report.
melanoma (4 papers, 2017 to 2022). A malignant, usually aggressive tumor composed of atypical, neoplastic melanocytes. "A specific gene, OR2C3, which contributes to such a biological pathway, has been confirmed to have an abnormally high expression pattern in melanoma, thereby confirming the distinctive function of such a pathway in unique subtypes of tumors." (PMID 30595815, 2019). "In addition, research evaluating the expression profile of olfactory receptors in a multitude of cancer cell lines has shown that OR2C3 is exclusively expressed in melanoma lines." (PMID 35805166, 2022). "Therefore, the pattern of OR2C3 expression implies a potential role in the initiation and/or development of melanoma." (PMID 35805166, 2022). "Remarkably, among cancer cell lines,OR2C3 is exclusively expressed in melanoma lines." (PMID 28492065, 2017). "Remarkably, the expression of OR2C3 was confirmed in human melanoma cells but in not normal melanocytes." (PMID 35805166, 2022).
acute lymphoblastic leukemia (1 paper, 2023). Leukemia with an acute onset, characterized by the presence of lymphoblasts in the bone marrow and the peripheral blood. "In acute lymphoblastic leukemia, mutations in OR2C3 have been associated with the development of the disease during childhood." (PMID 37370684, 2023).
cancer (2 papers, 2017 to 2024). A tumor composed of atypical neoplastic, often pleomorphic cells that invade other tissues. "The list of 78 also included five encoding membrane proteins, namely SLCO6A1, ZP4, OR2C3, OR1N1, and OR4N2, which are potential pan-cancer targets for CAR-T and antibody-drug conjugates." (PMID 39561714, 2024).